FOXA1 (forkhead box A1)
Diseases named in the same sentence as FOXA1 in open-access papers (continued):
Sharing a sentence is not in itself a finding about the gene and the disease.
lung cancer (continued). "FOXA1 is also involved in pancreatic cancer, lung cancer, liver cancer and other solid tumors by regulating AR and ER signaling pathways." (PMID 34991620, 2022). "Consistent with this, suppression of ID1 increased promoter occupancy of TCF4 and TWIST1 on E-box containing CDH1 and CDH2 promoter loci, and increased TCF4 and TWIST1 were observed on CDH1 and CDH2 promoters in FOXA1 knockdown A549 lung cancer cells." (PMID 35897813, 2022). "In this study, we measured the effect of FOXA1 expression on lung cancer cells survivability upon long term PBS treatment, which was routinely used to induce autophagy." (PMID 35974000, 2022). "In the previous description, we mentioned that FOXA1+ Tregs were found in lung cancer patients, which were reported earlier in EAE and MS models." (PMID 35474948, 2022). "Since ID1 is predominantly expressed in lung cancer among the ID family, we suggest that ID1 serves as an important factor on EMT induced by the loss of FOXA1 and PGC1α." (PMID 35897813, 2022). "Though the essence of FOXA1 expression for the lung cancer cells survival has been reported in the previous publications, our work highlighted an unusual role of FOXA1 in suppressing autophagic cell death of LUAD cells in nutrients poor conditions." (PMID 35974000, 2022). "More interestingly, the deletion of FOXA1 in KRAS-driven neoplasia derived from alveolar cells resulted in keratinizing squamous cell carcinoma, indicating that FOXA1/2 manipulated the growth of lung cancer in a context-dependent manner." (PMID 36012038, 2022). "A pilot study revealed that the expression level of FOXA1 is elevated in subpopulations of the A549 lung cancer cell line with high invasive potential." (PMID 35974000, 2022). "Consistent with the transcriptome analysis, decreased FOXA1 mRNA levels were observed in PGC1α-silenced A549 and H358 lung cancer cells." (PMID 35897813, 2022). "We demonstrated that FOXA1 enhanced lung cancer cell survival upon nutrients deprived conditions through suppressing autophagic cell death." (PMID 35974000, 2022). "In the present study, we found that TGFβ1, an essential EMT-promoting factor, suppresses PGC1α and FOXA1 expression in various lung cancer cells." (PMID 35897813, 2022). "Increased observations have revealed that FOXA1 (also known as HNF3A) is associated with EMT in multiple types of cancer, such as prostate, breast, pancreatic, and lung cancer." (PMID 35897813, 2022). "FOXA1 is a pioneer transcription factor that regulates cancer progression and differentiation, including liver, bladder, prostate, and lung cancers." (PMID 34006303, 2021). "FOXA1 promoted lung cancer development as a suppressor of the tumor immune microenvironment, which facilitates immune evasion of cancer cells." (PMID 32444802, 2020). "FOXA1 acts as a key transcription factor to regulate the progression of cancer in different cancers, such as breast, liver and lung cancer 38-42." (PMID 32308546, 2020). "These suggested that FoxA3 plays oncogenic function in lung cancer and esophageal cancer via elevation of FoxA1 and FoxA2 expressions." (PMID 32151057, 2020). "In lung cancer, FOXA1 and FOXA2 is involved in regulation of Epithelial to Mesenchymal genes relevant to cellular adhesion and cellular communication, and associated with distant metastasis." (PMID 33272232, 2020). "Lastly, when the genes for NKX2-1, FoxA1 and FoxA2 were deleted later, in lung tumors that had already formed, the outcome was a more aggressive type of lung cancer that also occurs in human patients." (PMID 30475207, 2018). "Although the current evidence can not support the regulation relationships between CSMD1 and FGG, it has been reported that the expression of FGG changed during EMT of lung cancer by several genes such as FOXA1 knockdown in A549 cells." (PMID 28959347, 2017).
lung cancer (continued). "This approach identified the forkhead box protein A1 (FOXA1) as the most significant TF during EMT in A549 lung cancer cells." (PMID 24093963, 2013). "We identified FOXA1 as a potentially important transcription factor and negative regulator in the initial stages of lung cancer metastasis." (PMID 24093963, 2013). "In the current study, we further investigated the role of FOXA1 in lung cancer." (PMID 39440051, 2024). "A previous study shows that simultaneous knockouts of Nkx2.1, FoxA1 and FoxA2 could induce squamous transition in Kras-driven lung cancer." (PMID 39687207, 2024). "Conversely, TGF-β1 can mediate EMT in lung cancer by suppressing FOXA1 expression." (PMID 38886389, 2024). "FOXA1 is also highly expressed in non–small cell lung cancer (NSCLC), but whether and how it regulates tumor growth in this context is not known." (PMID 37691854, 2023). "ID1, downstream of PGC1α and FOXA1, was also downregulated in TGFβ1-treated lung cancer cells." (PMID 35897813, 2022). "We do observe that FOXA1 expression help to maintain the phosphorylation status of IGF1R signaling cascade of lung cancer cells in the serum starvation conditions, which might be explained by increased IGF2 autocrine in lung cancer cells by FOXA1." (PMID 35974000, 2022). "Indeed, we found that loss of FOXA1 and PGC1α decreased E-cadherin and increased N-cadherin and vimentin expression, which was significantly reversed by ectopic ID1 expression in A549 lung cancer cells." (PMID 35897813, 2022). "A recent study reported increased numbers of FOXA1+ Tregs in patients with lung cancer." (PMID 35474948, 2022). "Similarly, decreased CDH1 and increased CDH2 were observed in FOXA1-silenced H358 lung cancer cells." (PMID 35897813, 2022). "Thus, our data along with the previous finding indicate that FOXA1 is a bona fide oncogenic factor contributing to lung cancer cell survival both in nutrients enriched and nutrients poor conditions." (PMID 35974000, 2022). "In light of recent evidence implicating PTC-introducing exons in lung cancer disease-free survival, we sought to investigate whether the subset of FOXA1-regulated NMD-determinant exons could impact PC patient prognosis." (PMID 36170835, 2022). "FOXA1 methylation was recently associated with the early detection of lung cancer but it is not extensively studied in this type of cancer." (PMID 34885084, 2021). "FOXA1 plays a crucial role in tumorigenesis of breast, prostate and lung cancers 2-5." (PMID 32929382, 2020). "In some cases of lung cancer, FOXA1 is overexpressed as a result of gene amplification." (PMID 32929081, 2020). "The negative association between Sox2 and FOXA1 has been demonstrated in human breast and lung cancers, in which Sox2 represses FOXA1 gene expression." (PMID 33553286, 2020). "FOXA1 is also reported to participate in the suppression of squamous identity in lung cancer." (PMID 32929382, 2020). "miR-194-5p regulation of FOXA1 is also observed in lung cancer." (PMID 30782188, 2019). "Thus, NKX2-1, FoxA1 and FoxA2 coordinately regulate the growth and identity of lung cancer in a context-specific manner." (PMID 30475207, 2018). "The involvement of ratio of FOXA1 to FOXA2 in lung cancer remains poorly known." (PMID 26658322, 2015). "The implication of FOXA1 in the epithelial-to-mesenchymal transition via its regulatory network indicates that FOXA1 may play an important role in the initiation of lung cancer metastasis." (PMID 24093963, 2013). "Here, we identified FOXA1 as an important TF involved in EMT during lung cancer progression." (PMID 24093963, 2013). "Moreover, FOXA1 functions as a negative regulator in the initial stages of lung cancer metastasis." (PMID 35804191, 2022). "Therefore, in lung cancer FOXA1 activity may be regulated by other regulators such as FOXA2 whose activities could be directly modulated through epigenetic mechanisms." (PMID 24093963, 2013).
lung cancer (continued). "Intriguingly, in lung cancer cells, RC48 not only impacts the HER2/PI3K/AKT pathway but also affects the FOXA1/HER2/PI3K/AKT pathway, thereby exerting a robust antitumor effect." (PMID 39440051, 2024). "This study mainly explores the relationship between FOXA1 and HER2 in lung cancer and the regulatory effects of RC48 on them, providing a potential basis for the treatment of lung cancer." (PMID 39440051, 2024). "This study also demonstrates that FOXA1 binds to the promoter region of HER2 and promotes its transcription in lung cancer." (PMID 39440051, 2024). "Thus, it is speculated that FOXA1 may function as an oncogene in lung cancer." (PMID 39440051, 2024). "This study demonstrates that FOXA1 directly binds to the promoter region of HER2, influencing the HER2/PI3K/AKT signaling pathway, which consequently modulates factors that foster lung cancer proliferation and impede apoptosis." (PMID 39440051, 2024). "FoxA1/2, another lineage-specifying transcription factor, drives gastric differentiation and suppresses squamous identity in NKX2-1-negative lung cancer." (PMID 38093367, 2023). "Because FOXA1 and PGC1α were found to regulate ID1, ID2, and ID3 in lung cancer cells, we investigated the mechanistic impact of ID1 on the loss of FOXA1-mediated EMT in lung cancer cells." (PMID 35897813, 2022). "Ectopic expression of FOXA1 increased ID1, ID2, and ID3 mRNA in A549, H358, and Calu-1 lung cancer cells." (PMID 35897813, 2022). "Here, we found that FOXA1 knockdown decreased CDH1 (epithelial marker) but increased CDH2, VIM, SNAI2, and PTHLH (mesenchymal markers) in A549 lung cancer cells." (PMID 35897813, 2022). "We analyzed the expression patterns between FOXA1 and DSCAM-AS1 using TCGA breast and lung cancer datasets." (PMID 32929382, 2020). "However, it remains unclear whether FOXA1 is involved in drug resistance in lung cancer." (PMID 32929081, 2020). "FOXA2 was involved in the functions including FOXA1 transcription factor network and cell communication, and FOXA2 was downregulated during EMT of lung cancer." (PMID 24093963, 2013). "More detailed functional and mechanistic studies are required to fully unveil the significance of FOXA1 during EMT and lung cancer progression." (PMID 24093963, 2013). "Beyond traditional HER2 or FOXA1-targeted therapies, ADC drugs such as RC48 could offer significant benefits to lung cancer patients and potentially transform the future treatment paradigm for lung cancer." (PMID 39440051, 2024). "The forkhead box A1 (FOXA1) protein is a member of a group of special transcription factors called pioneer factors; it is a crucial transcription factor in the initiation and development of breast, prostate, and lung cancers." (PMID 36998469, 2023). "FOXA1 and FOXH1 are members of FOX family of transcription factors, FOXA1 is decreased in hepatocellular carcinoma, FOXH1 promotes cell proliferation, invasion and tumorigenesis by enhancing the Wnt/β-catenin pathway in lung cancer cells and tissues." (PMID 37821907, 2023). "To understand the physiological relevance related to how decreased PGC1α, FOXA1, and ID1 promote metastasis via EMT in lung cancer, we speculated that TGFβ1, as a major EMT stimulus, could affect the suppression of PGC1α, FOXA1, or ID1." (PMID 35897813, 2022). "In addition, ectopic FOXA1 expression significantly reversed TGFβ1-mediated expression of EMT markers, such as CDH1, CDH2, VIM, SNAI2, and PTHLH, in A549 lung cancer cells." (PMID 35897813, 2022). "FOXA1 defines cancer specificity and regulates EMT in breast, prostate, and lung cancers." (PMID 35897813, 2022). "Studies showed that FOXA1 could regulate the expression of cell marker PLOD2 by binding to its promoters, thereby affecting the occurrence and development of lung cancer; (ii) T Marker: markers, which are regulated by TFs." (PMID 34986601, 2022).
lung cancer (continued). "Studies have shown that FOXA1 could regulate the expression of cell marker PLOD2 by binding to promoters, thereby affecting the occurrence and development of lung cancer." (PMID 34986601, 2022). "We found omentin to be consistently downregulated in lung cancers, and it exhibited a negative correlation with important transcription factors FOXA1, EN1, FOXC1 and ELK4." (PMID 33450975, 2021). "Specifically, FOXA1 plays a significant role in non-small cell lung cancer, MEF2 family members have a role in lung carcinoma, TEAD family members have known roles in carcinogenesis of epithelial tissues, and NKX2–1 has a long history of involvement in lung cancer, COPD and IPF." (PMID 34922464, 2021). "The precise mechanisms by which FoxA1/2 specifically activate a gastric program in NKX2-1 negative lung cancer, as opposed to other potential endodermal differentiation states (e.g. hepatic, pancreatic, lower GI tract etc.), remain to be determined." (PMID 30475207, 2018). "Interestingly, the top 5 most highly expressed SAE-enriched transcription factors all have previously been established as having a role in airway biology and/or lung cancer, including FOXJ1, ELF3, TRIM29, SOX2, and FOXA1." (PMID 22375630, 2012). "“PanCancer” panel (APC, FOXA1, RASSF1A) detected cancer with 72.4% sensitivity, 73.5% specificity and 72.8% accuracy.“CancerType” panel (SCGB3A1, SEPT9, and SOX17) discriminated TOO with 80.0%, 98.9%, and 85.1% specificity for breast, colorectal, and lung cancer, respectively." (PMID 36980276, 2023). "Thus, our findings demonstrate that FOXA1 and PGC1α-mediated transcriptional regulation of ID1 expression may involve energy metabolism in metabolic tissues as well as lung cancer metastasis." (PMID 35897813, 2022). "Thus, we speculate that cooperation between FOXA1 and PGC1α may participate in EMT-related gene expression by regulating ID1 expression in lung cancer cells." (PMID 35897813, 2022). "Silencing FOXA1 attenuates invasiveness and proliferation of the highly invasive A549 subpopulations even in conditions without serum starvation, suggesting that FOXA1-expressing lung cancer cells have survival advantage or proliferative phenotypes without treatment of serum starvation." (PMID 35974000, 2022). "Because loss of PGC1α was found to promote lung cancer metastasis to the bone by activating EMT in KrasG12V-driven lung cancer models as well as lung adenocarcinoma cells, we investigated whether FOXA1, a PGC1α interacting transcription factor, is involved in EMT in lung cancer cells." (PMID 35897813, 2022). "In addition, FOXA1 knockdown decreased ID1 and ID2 mRNA and protein levels in lung cancer cells." (PMID 35897813, 2022). "However, the precise molecular mechanism by which FOXA1 regulates EMT in lung cancer has not been fully elucidated." (PMID 35897813, 2022). "FOXA1 is one of the most significant transcription factors during epithelial-to-mesenchymal transition (EMT) and it is suggested that it may play an important role in the initiation of lung cancer metastasis." (PMID 34885084, 2021). "Interestingly, a cohort of these lung cancers showed that only higher expression of FOXA1, not FOXA2, linked with overall survival in all lung cancer, but not in lung ADCs and SCCs (data not shown)." (PMID 26658322, 2015). "Therefore, our analysis combining expression and TF regulatory data suggests that FOXA1 could be the potential negative regulator of EMT and could play pivotal roles in the initial steps of lung cancer metastasis." (PMID 24093963, 2013). "Interestingly, while HER2 does not regulate the expression of FOXA1, the introduction of RC48 significantly reduces the expressions of both HER2 and FOXA1 in lung cancer cells, indicating that RC48 can modulate both HER2 and FOXA1 expressions." (PMID 39440051, 2024).
breast tumors (52 papers, 2006 to 2026). "Given the highest ratio of FOXA1 mutations found in breast tumors and the expression specific to epithelial cell-specific pattern, we suspect that FOXA1 mutations initiate breast tumorigenesis." (PMID 41584858, 2026). "Focal amplification and hotspot mutations in FOXA1 occur in 3–6% of breast tumors and are associated with endocrine resistance." (PMID 34680352, 2021). "We found that BRCA1 deficiency correlates with the repression of FOXA1 expression in mammary epithelial cancer cell lines and that BRCA1 mutation is significantly associated with FOXA1 promoter methylation and silencing in human breast tumours." (PMID 25531315, 2015). "FOXA1 is a known pioneer cis co-factor for ERα binding and is frequently mutated in breast tumors." (PMID 31905229, 2020). "For example, we identified GATA3 and FOXA1 as highly linked TFs in breast tumors." (PMID 27833659, 2016). "FOXA1 gene has been shown to play a critical role in the subtyping and carcinogenesis of breast tumors." (PMID 40468582, 2025). "SCUBE2 was reported to work synergistically with FOXA1 as a novel breast-tumor suppressor, driving the reversal of epithelial–mesenchymal transition (EMT)." (PMID 37293596, 2023). "By activating interleukin-6, FOXA1 is downregulated, which results in breast tumor cells that are opposed to tamoxifen, having the characteristics of cancer stem cells." (PMID 37626655, 2023). "The data described so far imply the IGF1‐R/AKT pathway in Tel activity on FOXA1 and ERα protein levels and function and correlate FOXA1 with cell sensitivity to Tel antiproliferative effect in breast and non‐breast tumor cell lines." (PMID 36056637, 2022). "Accordingly, we found a positive correlation between FOXA1 and AR expression in breast tumors, while transient silencing of FOXA1 led to decreased AR mRNA expression levels in SNAI1-KO cells." (PMID 36171192, 2022). "In breast tumors and cell lines, expression of GATA3 is strongly associated with those of ESR1 and FOXA1." (PMID 34831189, 2021). "Patient data support this conclusion where breast tumors with decreased expression of FOXA1 were less proliferative, had reduced ERBB2/ERBB3 (HER2/HER3) expression, and increased enrichment of immune signatures." (PMID 34680352, 2021). "Though the choice of these loci was arbitrary for constructing the simulation, there is evidence that ESR1 and FOXA1 are highly co-expressed in breast tumors, and local-eQTLs of FOXA1 have been shown to be distal-eQTLs of ESR1." (PMID 33684137, 2021). "TWIST1 expression is negatively correlated with Foxa1 in human breast tumors, and tumors with high TWIST1 and low Foxa1 expression are associated with poor distant metastasis-free survival." (PMID 32565805, 2020). "A MEXPRESS analyses further indicated that FOXA1 expression is significantly upregulated in ER+ breast tumors compared with ER− tumors or normal tissues." (PMID 31562808, 2019). "Pathway analysis of these proteins, using KEGG datasets, revealed that aberration hubs found in luminal breast tumors are enriched in PI3K-Akt pathway and FOXA1 regulatory network, in line with a high prevalence of PIK3CA and FOXA1 mutations in this subtype." (PMID 29861861, 2018). "Immunohistochemical ERα, GATA3, and FOXA1 expression levels vary between primary breast tumors and paired metastases." (PMID 29972720, 2018). "Our findings have indicated that the majority of ERα binding sites in both male and female breast tumors are FOXA1-independent and are found at active promoter regions, indicating a novel and unexpected mode of ERα function." (PMID 29396493, 2018). "Consistently with this model, AR and FOXA1 mRNA expression positively correlated with percentage of ER and PgR expressing cells in our cohort of breast tumours, but only FOXA1 mRNA expression negatively correlated with miR-9-5p expression." (PMID 28345661, 2017).